HCG11 (HLA complex group 11)
Synonyms: bK14H9.3; FLJ14049; FLJ30357; CTA-14H9.3
Gene: Long non-coding RNA gene on chromosome 6 (26,521,709 to 26,527,404, forward strand). Ensembl gene ENSG00000228223.
Diseases named in the same sentence as HCG11 in open-access papers:
HCG11 is named in the same sentence as 30 diseases in open-access papers, as found by Europe PMC text mining. Sharing a sentence is not in itself a finding about the gene and the disease. The quoted sentences say what the papers report.
glioma (16 papers, 2019 to 2025). A benign or malignant brain and spinal cord tumor that arises from glial cells (astrocytes, oligodendrocytes, ependymal cells). "HCG11 has been linked to various health outcomes, including gastric tumors, glioma, and lung cancer." (PMID 40136322, 2025). "Previous studies have shown lncRNA HCG11 to be down-regulated in glioma tissues and cells, and this was associated with a lower survival rate in glioma patients." (PMID 33926464, 2021). "The same authors suggested that HCG11 acted as a competing endogenous RNA in glioma cells by sponging micro-496 to up-regulate cytoplasmic poly-adenylation element binding protein 3, which, together with miR-496 is involved in the progression of glioma." (PMID 37444408, 2023). "HLA complex group 11 (HCG11) is a recently identified lncRNA closely associated with gastric tumors, lung cancer, glioma, and cervical cancer; however, its roles of HCG11 in various tumors are distinct." (PMID 35463310, 2022). "The observed mechanism is for lncRNA HCG11 to suppress growth of glioma was by acting with the miR-4425 to release MTA3." (PMID 33926464, 2021). "Inversely, in glioma, HCG11 has been illustrated to limit the development of glioma in regulation of miR-496/CPEB3 axis." (PMID 34230221, 2021). "LncRNA HCG11 has been found to inhibit glioma progression through cooperating with miR‐496/CPEB3 axis." (PMID 32844573, 2020). "HCG11 suppresses the growth of glioma by interaction with miR-4425 to express MTA3." (PMID 35432537, 2022). "Additionally, HCG11 has been proposed to suppress the growth of glioma through cooperating with miR-4425/MTA3 axis." (PMID 34054958, 2021). "Low expression of lncRNA HCG11 has been found in glioma and prostate cancer." (PMID 34054958, 2021). "HCG11 modulated glioma progression through its action on the miR-496/CPEB3 axis." (PMID 33901010, 2021). "HCG11 was described to suppress the course of glioma by targeting miR-496/CPEB3." (PMID 33402177, 2021). "Similarly, lncRNA HCG11 has been reported to suppress the growth of glioma through cooperating with miR‐4425/MTA3 axis." (PMID 32844573, 2020). "HCG11 was studied in prostate cancer, glioma, and hepatocellular carcinoma." (PMID 31889902, 2019). "Furthermore, lncRNA HCG11 inhibited the progression of glioma and prostate cancer." (PMID 34054958, 2021). "Molecular factors such as miR-26a, HCG11, and PVT1 regulate endothelial cell behavior in the glioma microenvironment." (PMID 41272822, 2025). "HCG11 acts as a competing endogenous RNA by sponging miR-496, thereby upregulating cytoplasmic polyadenylation element binding protein 3 (CPEB3) in glioma cells." (PMID 41272822, 2025). "Neither lncRNA HCG11 nor PART1 have been investigated for a relationship with hsa-miR-129-5p and hsa-miR-490-3p in glioma." (PMID 33926464, 2021).
gastric cancer (10 papers, 2019 to 2023). A primary or metastatic malignant neoplasm involving the stomach. "For example, SOAT1 has been linked to the development of stomach cancer, and pancreatic cancer; HCG11 may influence the development of nasopharyngeal carcinoma; the PAQR6 gene has also been associated with several cancers." (PMID 37020999, 2023). "Based on previous literature, HCG11 was verified as a tumor suppressor in several malignancies, including gastric cancer and cervical cancer while HCG11 was also suggested as an oncogenic factor in ovarian cancer." (PMID 36874625, 2023). "LncRNA HCG11 has been experimentally demonstrated to facilitate the proliferation and migration of gastric cancer cells through the miR-1276/CTNNB1/Wnt pathway." (PMID 36693898, 2023). "From a cancer-promoting aspect, lncRNA HCG11 was highly expressed in gastric cancer tissues and cells, and lncRNA HCG11 silencing suppressed gastric cancer cell proliferation and migration by regulating the Wnt signaling pathway." (PMID 34949159, 2022). "In previous study, miR-1276 was found to be sponged by lncRNA HCG11 and regarded as a cancer suppressor in gastric cancer." (PMID 35687899, 2022). "LncRNA HCG11 was previously reported to be a tumor suppressor in prostate cancer and was shown to be dysregulated in cervical and gastric cancers." (PMID 34949159, 2022). "Besides, we also found that HCG11 was significantly abundant in advanced stages of gastric (III + IV) compared with that in gastric cancer early stages (I + II), indicating the crucial role of HCG11 in the development and progression of gastric cancer." (PMID 31889902, 2019). "In addition, Li and his team showed that lncRNA HCG11 could reverse the chemotherapy resistance of stomach cancer via the miR-144-3p/UBE2D1 pathway." (PMID 35342421, 2022). "Additionally, HCG11 was verified to sponge miR-942-5p to enhance BRMS1 expression, thus affecting the biological behaviors of gastric cancer cells." (PMID 36874625, 2023).
hepatocellular carcinoma (9 papers, 2018 to 2024). A malignant tumor that arises from hepatocytes. "LncRNA HCG11 effectively promoted tumor cell growth and metastasis in hepatocellular carcinoma by interacting with IGF2BP1." (PMID 34949159, 2022). "In hepatocellular carcinoma, HCG11 suppressed tumor cells apoptosis to promote the progression of hepatocellular carcinoma." (PMID 34230221, 2021). "Consistent with our results, decreased expression of lncRNA HCG11 has been identified in cervical cancer and hepatocellular carcinoma." (PMID 32844573, 2020). "HCG11 is significantly overexpressed in hepatocellular carcinoma (HCC) and genetic-silencing of HCG11 in HCC cells leads to decreased proliferation." (PMID 32591022, 2020). "In addition, HCG11 was found to suppress apoptosis via MAPK signaling transduction in hepatocellular carcinoma, and the downregulation of HCG11 expression predicts a poor prognosis in prostate cancer." (PMID 30764831, 2019). "A recent study has reported that a new lncRNA HCG11-derived oncogenic growth through interaction with the RNA-binding protein IGF2BP1, contributes in facilitating the ERK/MAPK pathway in hepatocellular carcinoma." (PMID 29416735, 2018).
prostate carcinoma (7 papers, 2019 to 2022). A carcinoma that arises from epithelial cells of the prostate gland. "In addition, downregulation of lncRNA HCG11 has been reported to be associated with poor clinical outcomes and prognosis in patients with prostate cancer, which is similar to our results." (PMID 32844573, 2020). "HCG11 was reported to work as an anti-oncogene in prostate cancer by sponging miR-543 and modulating AKT/mTOR pathway." (PMID 33402177, 2021). "Consistent with our results, downregulation of HCG11 has been identified in prostate cancer and predicted a poor prognosis." (PMID 34054958, 2021). "Forced overexpression of HCG11 in prostate cancer cells has suppressed cell proliferation, invasion and migration, while enhanced cell apoptosis by regulating miR‐543 expression." (PMID 32433496, 2020). "Functionally, overexpression of HCG11 has been found to inhibit cell proliferation, invasion and migration, whereas induce cell apoptosis in prostate cancer." (PMID 32844573, 2020). "Moreover, low lncRNA HCG11 expression was positively correlated with poor prognosis in prostate cancer patients, suggesting that lncRNA HCG11 may function as a prognostic biomarker of prostate cancer." (PMID 34949159, 2022).
breast carcinoma (6 papers, 2019 to 2025). "A study published in 2016 looking for lncRNAs as prognostic markers for human breast cancer has associated the poor overall survival (OS) with the expression levels (upregulation) of four lncRNAs, including NORAD (LINC00657) and HCG11." (PMID 33739352, 2021). "Our findings indicate that NORAD and HCG11 are differentially expressed in breast cancer subtypes and participate in distinct regulatory networks." (PMID 33739352, 2021). "Corroborating these findings by RT-qPCR, we observed a similar result in Brazilian breast cancer patients, and a recent study with 80 breast cancer patients showed that tumors with up-regulation of HCG11 were mostly ER-negative." (PMID 33739352, 2021). "One study reported that long non-coding RNA HCG11 is downregulated in HR-positive breast cancer tissues and cell lines, and HCG11 could inhibit the malignant progression of breast cancer in vivo and in vitro." (PMID 40176901, 2025). "HCG11, ranked 1st by CLING, has been identified as a significant prognostic marker in breast cancer." (PMID 32211391, 2020). "Thus, the functional role of HCG11 in breast cancer might be mediated through this miRNA." (PMID 32433496, 2020). "Here we investigated the expression profile of NORAD and HCG11 in tumor and non-tumor breast tissue RNA-seq datasets from TCGA, focusing on each breast cancer subtype and also in tumor samples from Brazilian patients." (PMID 33739352, 2021). "Finally, we selected four lncRNAs with higher predicted scores (NORAD, HCG11, ZNRD1ASP and TTN-AS1) and assessed their expression in 80 breast cancer tissues and their adjacent non-cancerous tissues (ANCTs)." (PMID 32433496, 2020).
cervical cancer (6 papers, 2020 to 2024). A primary or metastatic malignant neoplasm involving the cervix. "In terms of cancer inhibition, lncRNA HCG11 repressed cervical cancer cell proliferation and invasion by targeting miR-942-5p." (PMID 34949159, 2022).
lung cancer (4 papers, 2020 to 2025). A malignant neoplasm involving the lung. "Apart from the carcinogenic role, several LncRNAs also inhibited cancer progression, e.g., LINC01272 inhibited lung cancer, FUT8-AS1 inhibited melanoma and HCG11 suppressed non‐small cell lung cancer." (PMID 35012431, 2022).
pancreatic cancer (4 papers, 2020 to 2023). "Based on the results from expression and correlation analysis, NAMPTP1/HCG11-hsa-miR-26b-5p-COL12A1 competing endogenous RNA (ceRNA) sub-network was associated with the prognosis of pancreatic cancer." (PMID 33027767, 2020). "We speculated that HCG11/miR-579-3p/MDM2 axis could be an underlying therapeutic target in the treatment of pancreatic carcinoma." (PMID 34230221, 2021). "Herein, low expression of miR-579-3p was observed in pancreatic carcinoma tissues and cells, consistent with the findings in melanoma and lung squamous cell carcinoma, as well as negatively associated with the expression of HCG11." (PMID 34230221, 2021). "As expected, the apoptotic percentage of pancreatic carcinoma cells was significantly increased after knockdown of HCG11 (p<0.0001)." (PMID 34230221, 2021). "In a word, our study revealed that HCG11/miR-579-3p/MDM2 acted as a ceRNA network to promote the progression of pancreatic carcinoma by activating Notch/Hes1 pathway, further affirming the importance of MDM2/Notch/Hes1 in pancreatic carcinoma." (PMID 34230221, 2021). "Compared with HPDE6-C7 cells, we observed that HCG11 expression was highly increased in pancreatic carcinoma cells including BxPC-3, Capan-2, SW1990, PANC-1 and AsPC-1 (p<0.001)." (PMID 34230221, 2021). "After knockdown of HCG11, we observed that the OD values of pancreatic carcinoma cells were decreased significantly (p<0.01)." (PMID 34230221, 2021). "All these observations illustrated that HCG11 played an active role in the progression of pancreatic carcinoma." (PMID 34230221, 2021). "So, all these observations insinuated that HCG11 acted as an oncogenic lncRNA in pancreatic carcinoma progression." (PMID 34230221, 2021). "This study intends to explore the function and molecular mechanism of lncRNA HLA complex group 11 (HCG11) in pancreatic carcinoma." (PMID 34230221, 2021). "A marked augmentation of HCG11 was first discovered in both pancreatic carcinoma tissues and cell lines." (PMID 34230221, 2021). "Then, data from CCK-8, flow cytometry, plate cloning formation and Transwell assays suggested that upregulation of miR-579-3p suppressed the pro-oncogenic effect of HCG11 in pancreatic carcinoma cells." (PMID 34230221, 2021). "In our study, by applying bioinformatics analysis, we found several miRNAs potentially bind with HCG11, among which miR-579-3p was negatively regulated by HCG11 and was significantly downregulated in pancreatic carcinoma tissues and cells." (PMID 34230221, 2021). "Based on integrated bioinformatics analysis, a new potential COL12A-miR-26b-5p-HCG11/NAMPTP1 regulatory axis was successfully constructed in pancreatic cancer." (PMID 33027767, 2020). "Moreover, the biological function of HCG11/miR-579-3p/MDM2 in pancreatic carcinoma was analyzed by in vitro and in vivo models." (PMID 34230221, 2021). "Besides, we also discovered that depletion of HCG11 notably reduced the number of clones in pancreatic carcinoma cells (p<0.05)." (PMID 34230221, 2021). "Besides, we also detected that depletion of HCG11 reduced the invaded number of pancreatic carcinoma cells (p<0.05)." (PMID 34230221, 2021). "The results insinuated that depletion of HCG11 suppressed the growth of pancreatic carcinoma cells." (PMID 34230221, 2021). "In this study, we centered on exploring the effect of HCG11 in pancreatic carcinoma." (PMID 34230221, 2021). "Knockdown of HCG11 suppressed the progression of pancreatic carcinoma cells." (PMID 34230221, 2021). "Moreover, the data from flow cytometry assay indicated that suppression of HCG11 in pancreatic carcinoma cells controlled the cell cycle by inducing G0/G1 arrest compared with the siRNA NC group." (PMID 34230221, 2021). "In conclusion, the pivotal observations in this study illustrated that HCG11 increased the expression of MDM2 via competitively targeting miR-579-3p to promote the Notch/Hes1 pathway, thereby promoting the progression of pancreatic carcinoma." (PMID 34230221, 2021).
pancreatic cancer (continued). "Depletion of HCG11 reduced MDM2 expression at transcription and translation levels in pancreatic carcinoma cells." (PMID 34230221, 2021). "Significantly, a marked augmentation of HCG11 expression was observed in pancreatic carcinoma tissues when compared with the corresponding non-cancerous tissues (p<0.001)." (PMID 34230221, 2021). "Therefore, in our study, the expression of HCG11 and its potential target miR-579-3p/MDM2 were analyzed in clinical pancreatic carcinoma and corresponding para-carcinoma tissues." (PMID 34230221, 2021). "However, the expression and mechanism of HCG11 in pancreatic carcinoma remain not elucidated." (PMID 34230221, 2021). "Based on the ceRNA hypothesis, a novel HCG11/NAMPTP1-miR-26b-5p-COL12A1 triple sub-network was constructed, which showed that overexpressed lncRNAs/pseudogenes mediate downregulation of hsa-miR-26b-5p leading to increased expression of COL12A1 in the progression of pancreatic cancer." (PMID 33027767, 2020).
nasopharyngeal carcinoma (3 papers, 2022 to 2025). A carcinoma arising from the nasopharyngeal epithelium. "High and low HCG11 expression in nasopharyngeal carcinoma in the study population (n = 126) and stratified according to demographic and clinical variables." (PMID 35463310, 2022). "This study aimed to elucidate the functional mechanisms of the HLA complex group 11 (HCG11) in nasopharyngeal carcinoma (NPC)." (PMID 35463310, 2022). "A recent study found high levels of HCG11 expressed in nasopharyngeal carcinoma tissues." (PMID 40136322, 2025).
osteosarcoma (3 papers, 2021 to 2022). A usually aggressive malignant bone-forming mesenchymal neoplasm, predominantly affecting adolescents and young adults. "Moreover, HCG11 promotes the expression of MMP13 and exacerbates osteosarcoma through sponging miR-579." (PMID 35359458, 2022).
lung adenocarcinoma (2 papers, 2022 to 2023). A carcinoma that arises from the lung and is characterized by the presence of malignant glandular epithelial cells. "In addition, LncRNA human leukocyte antigen complex group 11 (HCG11) served as a tumor suppressor to restrain tumor growth in lung adenocarcinoma." (PMID 37365581, 2023).
lymph node metastasis (2 papers, 2017 to 2022). "In this study, HCG11 was positively correlated with advanced stage and lymph node metastasis and negatively associated with NPC patient survival." (PMID 35463310, 2022). "We found a positive correlation between HCG11 expression and lymph node metastasis and further investigated the role of HCG11 in cell migration." (PMID 35463310, 2022).
Vestibular schwannoma (2 papers, 2021 to 2025). A vestibular schwannoma (also known as acoustic neuroma, acoustic neurinoma, or acoustic neurilemoma) is a benign, usually slow-growing tumor that develops from the VIIIth cranial nerve supplying the inner ear. "Conversely, ELK4 functions as a tumor suppressor in vestibular schwannoma by promoting HCG11 transcription, thereby inhibiting cell proliferation and inducing apoptosis." (PMID 41502523, 2025). "The rescue assays illustrated the effectiveness of HCG11/miR-620/ELK4 axis in vestibular schwannoma." (PMID 33402177, 2021).
ischemia (1 paper, 2025). A hypoperfusion of the BLOOD through an organ or tissue caused by a PATHOLOGIC CONSTRICTION or obstruction of its BLOOD VESSELS, or an absence of BLOOD CIRCULATION. "Studies with lncRNA HCG11 downregulation showed that it inhibited the growth of neuroinflammatory factors, limited infarct size, and improved neurological outcomes after ischemia." (PMID 41245147, 2025).
measles (1 paper, 2023). A highly contagious viral infection caused by the measles virus. "In measles, including six in whole blood (SOAT1, COLGALT2, AC021860.1, HCG11, METTL21B, and MRPL10), six in the lung tissue (GSTM4, PAQR6, RP11-617D20.1, SNX8, METTL21B, and ANKRD27), and two in the transformed fibroblast cells (CBWD2, and TSFM)." (PMID 37020999, 2023).
myelofibrosis (1 paper, 2022). A partial or complete replacement of the bone marrow stroma by fibrous tissue. "Both class I and II HLA genes are down‐regulated in PV, ET and myelofibrosis, with progressive downregulation of certain genes [BAT2L, HLA Complex Group 11 (HCG11) and major histocompatibility complex (MHC), Class I‐related (MR1)] in ET versus PV versus myelofibrosis." (PMID 34618358, 2022).
rhinitis (1 paper, 2025). An inflammation of the mucous membrane lining the nose, usually associated with nasal discharge. "For rhinitis, cg15790214 (HCG11) was shown to play such a role as a mediator (β = −0.027, p ≤ 0.0001; OR = 0.22, 95% CI 0.07–0.72, p = 0.01)." (PMID 40136322, 2025).